MIR4793 (microRNA 4793)
Synonyms: hsa-mir-4793
Gene: MicroRNA gene on chromosome 3 (48,644,194 to 48,644,280, reverse strand). Ensembl gene ENSG00000284575.
Homologues: Orthologues: chimpanzee MIR4793 (100% identical).